MTOR (mechanistic target of rapamycin kinase)
Diseases named in the same sentence as MTOR in open-access papers (continued):
Sharing a sentence is not in itself a finding about the gene and the disease.
polycystic kidney disease (36 papers, 2008 to 2026). A usually autosomal dominant and less frequently autosomal recessive genetic disorder characterized by the presence of numerous cysts in the kidneys leading to end-stage renal failure. "mTOR activation is known to generate polycystic kidneys, which show both increased proliferation and loss of oriented cell division (OCD)." (PMID 32581239, 2020). "Disruption of MTOR signaling has been documented in numerous pathological conditions, including cancer, neurological disorder, and metabolic disorder Polycystic kidney disease (PKD) patients with inherited mutations in ciliary genes show deregulation of the MTOR signaling pathway." (PMID 31139054, 2019). "Although mutations in the PI3K/AKT/mTOR pathway are highly characterized in cancer, recent evidence indicates that alterations in the proliferative signals are major drivers of other diseases such as overgrowth disorders and polycystic kidney disease." (PMID 28353628, 2017). "Pkd-1 mutations can also result in triggering of the mTOR pathway and have been linked to cell proliferation and the development of polycystic kidney disease; blocking mTOR with rapamycin can substantially inhibit the proliferation of cysts in mice with this conditionally expressed mutation." (PMID 25699174, 2015). "Mutations in the PI3K/Akt/mTOR pathway may cause polycystic kidney disease." (PMID 31894918, 2019). "In polycystic kidney disease, targeting ciliary dysfunction through cAMP modulation, growth factor inhibition, microRNA-17 inhibition, and mTOR inhibition has demonstrated therapeutic potential." (PMID 40277920, 2025). "The green cluster covers folliculin, flcn, BHD gene, expression, mTOR activation, identification, protein, polycystic kidneys." (PMID 35479937, 2022). "Numerous anti-proliferative drugs, such as rapamycin (mTOR inhibitor) and octreotide (somatostatin analog), have been used to treat polycystic kidney animal models in recent years." (PMID 30886744, 2019). "The mTOR inhibitor rapamycin is known to reduce cysts in teleost and mammalian models of polycystic kidney disease, while in clinical trials in humans, it demonstrated limited efficacy as a therapeutic drug." (PMID 30875791, 2019). "Inhibition of mammalian target of rapamycin (mTOR) slows polycystic kidney disease (PKD) progression in animal models, but randomized controlled trials failed to prove efficacy of mTOR inhibitor treatment." (PMID 29615724, 2018). "PI3K/AKT/mTOR is frequently deregulated in several proliferative disorders, from cancer to overgrowth syndromes and polycystic kidney disease." (PMID 28353628, 2017). "In this review, we report the recent findings in PI3K/AKT/mTOR pathway alterations, not only in the well-known context of cancer, but also in other proliferative disorders such as overgrowth syndrome and polycystic kidney disease." (PMID 28353628, 2017). "Further precise investigation into the effects of mTOR inhibitors on polycystic kidney disease is needed to enable their clinical application." (PMID 27338360, 2016). "This is consistent with the published data from the studies in models of diabetic and polycystic kidney disease suggested that inhibition in mTOR activity slowed down the progression of tubulointerstitial fibrosis." (PMID 25149531, 2014). "The mammalian target of rapamycin (mTOR) signaling pathway is aberrantly activated in polycystic kidney disease (PKD)." (PMID 24009738, 2013). "Studies have shown aberrant activation of mTOR in several rodent models of polycystic kidney disease and treatment with rapamycin has been shown to alleviate cyst enlargement in murine models." (PMID 20169078, 2010). "As suppressed autophagy and increased mTOR play a role in kidney cyst growth in polycystic kidney disease, our original hypothesis was that Atg7−/− kidneys would be cystic." (PMID 40496859, 2025).
polycystic kidney disease (continued). "In experimental studies, ketogenic interventions successfully reduced disease progression in polycystic kidney disease animal models, possibly by lowering glucose availability in renal tubular cells and by reducing mammalian target of rapamycin (mTOR) signaling." (PMID 37974030, 2024). "Polycystic kidney disease (PKD) has been described as a “neoplasia in disguise” that may be related to perturbed mTOR signaling." (PMID 37145994, 2023). "The pathway of mTOR inhibition may also provide novel strategies for managing autosomal dominant polycystic kidneys." (PMID 37240765, 2023). "Furthermore, treatment of ADPKD transplant-recipient patients with mTOR inhibitor was associated with significant reduction of the size of the endogenous polycystic kidney, indicating the key role of mTOR in ADPKD pathology." (PMID 32276433, 2020). "Given that rapamycin – an mTOR inhibitor, shows efficacy in several rodent models of polycystic kidney disease it would be interesting to determine if these renal cystoproteins act at or upstream of the PC1-TSC2 node of the pathway, implicating PC1-TSC2 as a pathogenic nexus in these disorders." (PMID 20169078, 2010). "This interpretation would be compatible with the limited activity of inhibitors of the S6 activator mTOR, or inhibitors of SRC, in assessment for treatment of polycystic kidney disease." (PMID 26528438, 2015). "Before investigating the correlation of FLCN with mTOR pathway, we first examined the distribution of FLCN in normal mouse kidney and polycystic kidney." (PMID 18974783, 2008). "Although treatment with mTOR inhibitors has shown positive results in preventing massive renal enlargement in a variety of polycystic kidney disease (PKD) animal models, clinical trials have not been able to show the same beneficial effect of mTOR inhibitors treatment in ADPKD patients." (PMID 29615724, 2018).
acne (34 papers, 2016 to 2026). An inflammatory process of the sebaceous glands which is characterized by comedones, nodules, papules and/or pustules on the skin. "Others such as platycodin D, lupeol, etc., have been identified for their anti-acne effect through their inhibition of the PI3K/AkT/mTOR and associated pathway." (PMID 37371141, 2023). "Since a high glycemic load diet is linked to mTOR overexpression, further understanding of the impact of the Western diet on acne and evaluation of the therapeutic response to acne treatment is required." (PMID 35163615, 2022). "A study has demonstrated the potential association of IGF-I, mammalian target of rapamycin (mTOR), and FoxO1 in the pathogenesis of acne via immunohistochemical detection." (PMID 34418600, 2021). "Mechanistic target of rapamycin (mTOR), a major regulator of cellular protein and lipid metabolism, has been reported to increase in the sebaceous glands of acne patients." (PMID 40817681, 2025). "The gut microbiota plays an important role in the pathophysiology of acne vulgaris, potentially via interaction with the mTOR pathway." (PMID 41178942, 2025). "Overproduction of ROS is involved in the pathogenesis of acne vulgaris via various pathways, including activation of mTOR, peroxisome proliferator-activated receptors (PPARs), and toll-like receptors (TLRs)." (PMID 41178942, 2025). "Excess lipid accumulation in ASCs and sebocytes stimulates the release of pro-inflammatory cytokines, such as TNF-α and IL-6, aggravating skin inflammation, promoting sebaceous gland activity, and exacerbating acne through mTOR signaling activation." (PMID 40227405, 2025). "The researchers mentioned that mTOR expression is increased in immunohistochemical studies in patients with acne at both the nuclear and cytoplasmic levels." (PMID 38646331, 2024). "The interaction between metabolites generated by gut microbiota and mammalian target of rapamycin (mTOR) signaling pathways has been demonstrated to influence intestinal microbiota composition and have consequences for acne pathogenesis." (PMID 38788015, 2024). "Such microbial interactions and the resultant modulation of cell expansion and metabolism, particularly through the mTOR signaling pathway, underscore a deeper link between gut dysbiosis and acne inflammation." (PMID 38791344, 2024). "IGF-1 is a key player in acne pathogenesis, and the IGF-1-induced PI3K/Akt/FoxO1/mTOR C1 pathway is considered to be the most important pathway leading to acne pathogenesis." (PMID 38585341, 2024). "Among them, IGF-1, IGF-1R and downstream mechanistic target of rapamycin (mTOR) play key roles in the development of acne and the formation of acne-induced PSs." (PMID 38585341, 2024). "Several natural dietary product supplements have been described as anti-acne agents, which target the mTOR signaling pathway." (PMID 37371141, 2023). "In patients with acne, both cytoplasmic and nuclear mTOR expression are generally markedly higher than in controls." (PMID 38130575, 2023). "It has been shown that oxidative stress is involved in the pathogenesis of acne through several pathways such as PPARs, TLRs, mTOR and the innate immune system." (PMID 35630086, 2022). "In patients with acne, both cytoplasmic and nuclear mTOR expression was considerably higher than in controls." (PMID 35163615, 2022). "SREBPs and PI3KCA are activated via Forkhead box transcription factor (Fox) O1 expression and the mammalian target of rapamycin (mTOR) that are increased in acne affected individuals." (PMID 35910763, 2022). "The PI3K/Akt/FoxO1/mTORC1 of the Mammalian Target of Rapamycin (mTOR) C1 pathway induced by IGF-1 is known to be involved in the pathogenesis of acne." (PMID 35966699, 2022). "The mTOR pathway is a central regulator of cellular protein and lipid metabolism, and its key regulatory mTORc1 complex is upregulated in acne sebaceous glands." (PMID 35328573, 2022).
acne (continued). "One pathway suggested to influence acne is the mechanistic target of rapamycin (mTOR) pathway when interacted with by intestinal flora." (PMID 33173621, 2020). "Such trials should use harmonized severity measures and incorporate mechanistic endpoints—such as microbiome profiling, inflammatory biomarkers, and IGF-1/mTOR signaling assays—to clarify the pathways through which probiotics may influence acne." (PMID 41470154, 2025). "Studies have shown that skin inflammation may be caused by small changes in a certain bacterial species in the gut microbiome, and experiments have shown that the gut microbiome affects the development of acne through the mTOR pathway." (PMID 38371936, 2024). "The intestinal flora's influence on acne is speculated to involve interactions with the mammalian target of rapamycin (mTOR) pathway." (PMID 38556870, 2024). "C. acnes initiates the inflammatory process of acne pathogenesis by triggering the production of ROS and inflammatory cytokines via Toll-like receptor 2, peroxisome proliferator-activated receptor, the mTOR pathway, and the innate immune system." (PMID 37514071, 2023). "Moreover, mTOR expression steadily increases during the transition from a healthy state to lesional acne skin." (PMID 38130575, 2023). "A possible influence of the gut microbiota in acne may be an interaction with the mTOR (mammalian target of rapamycin) pathway." (PMID 35889022, 2022). "Considering the possible role of mTORC1 in acne pathophysiology, the interaction between mTOR and gut microbiota may serve as a mechanism by which the intestinal flora aggravates acne." (PMID 31284694, 2019). "Hence, agents that can target mTOR are potent anti-acne therapeutic options that act via multiple pathways of acne pathomechanism." (PMID 34466486, 2019). "This study reviews the evidence for the pivotal role of oxidative stress in the pathogenesis of acne vulgaris and suggests that oxidative stress can considerably contribute to the pathobiology of acne vulgaris via various pathways including PPARs, TLRs, mTOR and innate immune system." (PMID 34466486, 2019). "The intestinal flora is thought to influence acne, possibly by interacting with the mTOR pathway." (PMID 31284694, 2019). "The interplay between mTOR and gut microbiota may form a mechanism by which the intestinal flora exacerbates acne, particularly in cases of gut dysbiosis and a disrupted intestinal barrier, creating a positive feedback loop and amplifying host metabolism and inflammation." (PMID 38556870, 2024). "Therefore, AMPs could be key determinants in regulating AV development and progression, linking acne-associated immune responses and metabolic factors, like insulin/IGF-1 and PI3K/Akt/mTOR/FoxO1 signaling pathways or glucotoxicity." (PMID 39744637, 2024). "Therefore, AMPs may be key determinants in developing and progressing acne-associated immune responses, skin barrier integrity, and metabolic factors, like insulin/IGF-1 and PI3K/Akt/mTOR/FoxO1 signaling pathways or high glucose levels." (PMID 39744637, 2024). "Gut microbiota probably contribute to acne by interacting with the mTOR signalling pathway, and bacterial metabolites may control cell growth, lipid metabolism, and other metabolic functions via the mTOR pathway." (PMID 36558452, 2022). "Some target genes were likely involved in acne development, including AR, IGF1/IGF1R, mTOR, GATA6, Wnt, IL6, FOXO1, PIK3, MYC." (PMID 40625748, 2025). "The PI3K/Akt/FoxO1/mTORC1 axis of the Mammalian Target of Rapamycin (mTOR) C1 pathway, induced by IGF-1, is known to be an essential signaling pathway for the pathogenesis of acne." (PMID 35966699, 2022). "As in other inflammatory skin conditions like psoriasis vulgaris, acne, atopic dermatitis, and hidradenitis suppurative, we found in active lesions of CLE an increased expression of IRF4 in the dermis and mTOR in the epidermis." (PMID 34944673, 2021).
acne (continued). "In affected and non-affected acne skin lower expression of PPARγ and hyper-activation of mechanistic target of rapamycin (mTOR) signaling have been detected." (PMID 36439142, 2022). "In fact, Monfrecola research group provided experimental evidence for increased mTOR expression and S6K1 phosphorylation (and thus increased mTORC1 signaling) in acne group compared to acne-free healthy controls, which was also recently proved by other researchers." (PMID 27803511, 2016). "Hence, our findings suggest that BV and melittin inactivate IGF-1R/Akt/mTOR/SREBP and this is likely to be important in the anti-lipogenic action against C. acnes or IGF-1, offering therapeutic strategies to target lipogenesis in acne." (PMID 35328573, 2022). "Furthermore, mTOR, FoxO1, and serum IGF-1 along with a high-glycemic-load diet may be involved in the development of acne." (PMID 35163615, 2022). "Another group has shown that mTOR gene expression is 17.96- and 20.77-fold higher in nonlesional (NLS) and lesional skin (LS), respectively, from 10 acne patients when compared to skin samples from healthy subjects." (PMID 35163615, 2022).
fibrosis (34 papers, 2014 to 2025). the formation of excess fibrous connective tissue in an organ or tissue in a reparative or reactive process. "Sarcoidosis modelling is carried out in vitro using human lung cells and in vivo in mice with the experimentally induced fibrosis and lung granulomas, as well as in animals with impaired expression of the Tcs2 gene—an activator of the mTOR signalling pathway." (PMID 37511027, 2023). "It was found significant that these hub genes caused the M2-type polarization of macrophages by activating the PI3K-Akt-mTOR pathway, and then led to hepatic fibrosis and participated in the development of HCC." (PMID 36439183, 2022). "The main feature of the uterine fibrosis process is collagen deposition, determined primarily by estrogen, a Pi3k/Akt/mTor signaling pathway activator." (PMID 31955151, 2020). "The cardiac dysfunction is mediated by increased PLN phosphorylation at threonine 17 and serine 16, as well as inhibition of Akt/mTOR signaling and autophagic activity, leading to cardiac fibrosis, cardiac myocyte apoptosis, and oxidative stress." (PMID 32716920, 2020). "mTOR activation contributes to type I collagen production by dermal fibroblasts, and rapamycin improves skin fibrosis in two mouse models of fibrosis." (PMID 28228756, 2017). "p-S6 expression was also more significantly increased in the lungs of bleomycin-treated mice compared with control mice, indicating that mTOR signaling was also overactivated in the bleomycin-mediated lung injury and fibrosis model." (PMID 26382847, 2015). "The histological fibrosis scores and lung function decline in the strong mTOR expression group were higher than those in the weak and intermediate expression group." (PMID 25358403, 2014). "Moreover, the ononin that originated from astragali radix (Huang-qi) was proven to inhibit cardiac fibrosis via the AMPK/mTOR signaling pathway." (PMID 34925028, 2021). "This in turn suppresses hepatic PPARα-FGF21 signaling and activates the cardiac mechanistic target of rapamycin (mTOR)/ L-type amino acid transporter 1 (LAT1) pathway, contributing to cardiac fibrosis and dysfunction." (PMID 40878016, 2025). "Thus, AKT/mTOR may be involved in the regulation of cardiac fibrosis." (PMID 40471098, 2025). "Cardiac function, cardiac fibrosis, apoptosis, and expression of p-AMPK, p-mTOR, and autophagy-related proteins was measured after 4 weeks of treatment after the successful modelling of the AMI." (PMID 32285737, 2020). "p-mTOR levels were significantly increased and LC3-II, p-Akt, and Beclin1 levels were significantly decreased in the PQ-induced fibrosis group in contrast to the control group (p < 0.01)." (PMID 30744607, 2019). "The expression of mTOR and ZEB1 significantly correlated with the fibrosis score and pulmonary function change." (PMID 25358403, 2014). "In our study, expression of mTOR was increased in most of the UIP lung tissues and significantly correlated with the fibrosis score and pulmonary function change." (PMID 25358403, 2014). "In summary, the present study provided evidence for the alleviating effects of CGGD on CP through multiple mechanisms, including reducing pancreatic damage, preventing pancreatic fibrosis, and inhibiting PSC autophagy and activation through the JNK/mTOR pathway." (PMID 34177589, 2021). "While splenic fibrosis was in agreement with our study, our results do not implicate genes related to mTOR signaling in splenomegaly." (PMID 30573742, 2018). "In this report, we found that mTOR inhibitor rapamycin or mTOR deletion in CX3Cr1+ mononuclear phagocytes inhibits expression of interleukin (IL) −23, accompanied by reduced intestinal production of IL-22 and ameliorated fibrosis in the TNBS-induced fibrosis mouse model." (PMID 30765845, 2019). "Assays of colon tissues from CD patients showed that intestinal fibrosis was greater in stenoses than in nonstenoses, with upregulation of p-AKT, AKT, p-mTOR, mTOR, p-ERK1/2, ERK1/2, p-PKC, and PKC targets." (PMID 35450039, 2022).